S100A11 (S100 calcium binding protein A11)
Diseases named in the same sentence as S100A11 in open-access papers (continued):
Sharing a sentence is not in itself a finding about the gene and the disease.
tumor (103 papers, 2008 to 2026). "We show that extracellular S100-A11 promotes tumour cell proliferation and is associated with activation of the RAGE/STAT3 signalling axis." (PMID 42155177, 2026). "In this context, we describe a paracrine signalling interaction in which CAF-associated S100-A11 is linked to activation of the RAGE/STAT3 axis in tumour cells, accompanied by increased proliferation and reduced sensitivity to treatment." (PMID 42155177, 2026). "S100A11, a calcium-binding protein, has been associated with inflammatory signaling and modulation of tumor proliferation and migration." (PMID 40710368, 2025). "S100A11 is associated with tumor-cell proliferation, migration, invasion, and therapeutic resistance across multiple cancers." (PMID 41514658, 2025). "We traced the spatial distribution of these nonsynonymous mutations and observed that although KRAS and S100A11 were expressed in various regions, the mutated gene form was mainly restricted in the tumor regions, suggesting potential neoantigens." (PMID 40515555, 2025). "In contrast, other S100 proteins such as S100A6, S100A8, S100A9, and S100A11 are frequently upregulated in various malignancies, including BC, where they are linked to tumor-promoting functions." (PMID 41404073, 2025). "In the majority of malignancies, elevated S100A11 expression levels are closely associated with tumor promotion and progression." (PMID 40747341, 2025). "Because several studies have reported that S100A11 was associated with tumour stem cells, we tested its effect on spheroid formation and observed that its knockdown markedly impaired the ability to form spheroids." (PMID 35752610, 2022). "Overexpression of S100A11 is associated with tumor stage, drug resistance, high TP 53 mutation, and shorter overall survival." (PMID 34804125, 2021). "A recent study showed that S100A11 overexpression promoted inflammation/fibrosis and was associated with tumor grade and poor survival time of HCC patients." (PMID 33815482, 2021). "S100A11 is associated with the oncogenesis of many different types of tumour and has been identified as a tumour suppressor in some cancers and as a tumour promoter in other cancers." (PMID 28446208, 2017). "Overexpression of S100A11 in cytoplasmic and nuclear subcellular compartments is associated with tumor metastasis and poor prognosis of CRC patients." (PMID 27181092, 2016). "To further explore the function and role of FLOT1 and histone H1 in S100A11-mediated tumor progression, we performed gain- and loss-of-function assays." (PMID 27181092, 2016). "A causative role for subcellular localization of S100A11 in an experimental animal model was investigated by subcutaneous injection and tail vein injection of tumor cells." (PMID 27181092, 2016). "Overexpression of S100A11 has been identified in a variety of human cancer types and elevated S100A11 expression is closely associated with tumor progression." (PMID 25780452, 2015). "In NSCLC, S100A11 is also overexpressed, and its high expression was associated with a higher tumor-node-metastasis stage and positive lymph node status." (PMID 25940438, 2015). "S100A11 protein is a calcium-binding protein implicated in a variety of biological functions such as proliferation and differentiation, whose relation with tumor progression and invasion was substantiated by recent proteomics studies." (PMID 21342498, 2011). "Elevated levels of crucial genes such as INHBB, CCDC80, and S100A11 could be significantly linked to tumor development, progression, and the modulation of the tumor microenvironment." (PMID 39850875, 2024). "In the same study, a tendency toward the same evolution was observed for S100A4, while two other proteins in the S100 family, encoded by the S100a6 and S100a11 genes, exhibited a similar increase in untreated tumor-bearing rats, which was completely reversed upon curcumin treatment." (PMID 35873564, 2022).
tumor (continued). "The dysregulated expression of the S100A11 gene has been implicated in tumour metastasis." (PMID 33931048, 2021). "Moreover, S100A11 was associated with an immunosuppressive tumor microenvironment." (PMID 40567612, 2025). "In a reductionist xenograft model, RAGE inhibition with azeliragon attenuated the effect of exogenous S100-A11 on tumour response to TPD." (PMID 42155177, 2026). "The results revealed that S100A11 was expressed mainly in tumor cells, monocytes/macrophages and fibroblasts in GSE160269." (PMID 39981252, 2025). "On the contrary, we observed a 50% reduction of tumor volumes in the animals knocked down for S100A11." (PMID 40841353, 2025). "S100A11 silencing significantly decreased the growth rate and the tumour volume, implying lower proliferative ability." (PMID 40374593, 2025). "Conversely, S100A11 overexpression resulted in increased tumour growth, with larger and heavier tumours in the group overexpressing S100A11 compared to the vector control group." (PMID 40374593, 2025). "A significant increase in hypercellular areas was observed in GBM with high expression of S100A11, and there was a positive correlation between S100A11 expression and the proliferative and mitotic index, as measured by IHC with the tumor marker MIB-1." (PMID 39744679, 2025). "The therapeutic effect of combined S100A11 knockout in both tumor cells and CAFs was significantly superior to knockout in tumor cells alone." (PMID 41154598, 2025). "Ki-67 and S100A11 immunostaining demonstrated decreased proliferation in S100A11-silenced tumours, as indicated by lower Ki-67 expression, whereas tumours overexpressing S100A11 revealed increased Ki-67 levels indicating enhanced proliferation." (PMID 40374593, 2025). "While the knock-down of S100A10 resulted in increased size of the nodules, S100A11 downregulation reduced tumor growth, consistent with the LPTENKO model, underscoring a MASLD-independent effect." (PMID 40841353, 2025). "qRT-PCR analysis showed that compared to neighboring normal tissues, the tumor tissue the S100A11 mRNA level was increased 3.2-fold (p<0.001)." (PMID 40567612, 2025). "In this study, we observed a strong association between high S100A11 expression and immunosuppressive microenvironmental traits, and that knockdown of S100A11 inhibited tumor cell proliferation and enhanced apoptosis." (PMID 40567612, 2025). "The tumour volume data confirmed the significant increase in growth rate for the S100A11 overexpression group." (PMID 40374593, 2025). "In DEN-treated mice, S100A10 and S100A11 were downregulated at 7 months (before tumor formation) up to 11 months of age (time of sacrifice)." (PMID 40841353, 2025). "In order to identify possible oncogenes/drivers (ONC/D) or tumor suppressors (TS) modulated specifically by S100A10 or S100A11, we processed the proteomic data using CancerMine database." (PMID 40841353, 2025). "S100A11 is overexpressed in lung, cervical, colorectal and pancreatic cancers, where it facilitates tumour growth and invasion." (PMID 40374593, 2025). "This study aims to identify exosome-related biomarkers in CRC and elucidate the functional significance of S100A11 in tumor progression and immune regulation." (PMID 40567612, 2025). "Transient S100A11 overexpression partially but significantly rescued the USP14 knockdown-induced tumour growth suppression." (PMID 40374593, 2025). "Bottom: Both UMAP projection and violin plot highlighting the specific expression of S100A11 in tumor cells." (PMID 40515555, 2025). "S100A11 deficiency impairs cell proliferation and invasion in CRC, inhibiting tumour growth in a xenograft model." (PMID 40374593, 2025). "Subsequently to evaluate the role of S100A11 in tumour metastasis in vivo BALB/c nude mice were injected intravenously in the tail vein with SW620 cells stably expressing either control or S100A11 shRNA." (PMID 40374593, 2025).
tumor (continued). "Inhibition of Akt reduced the pro-tumour effect of exosomal S100A11 from LAP-M in both 4T1 and Py8119 models." (PMID 39756316, 2024). "Compared to M0 or M2 type macrophages, LAP-competent macrophages (LAP-M) exhibited an enhanced pro-tumour phenotype mediated by the release of exosomal S100A11." (PMID 39756316, 2024). "By transferring exosomal S100A11 into the living tumour cells after chemotherapy, the macrophage exhibits a more pro-tumour phenotype than classic M2-type macrophages." (PMID 39756316, 2024). "Among them, S100A11 showed the highest expression level and was reported to regulate tumour cell invasion." (PMID 39756316, 2024). "Functional characterization both in vitro and in vivo validated S100A11 as one of the top downstream mediators for tumor initiation and stemness maintenance of this subclone." (PMID 38169544, 2024). "After dissociating the HCC tumor, we observed a significant increase in M1 macrophages upon S100A11 knockdown whereas the total tumor infiltrating macrophages remained unchanged." (PMID 38169544, 2024). "A previous study demonstrated the dual role of S100A11 in tumour metastasis arrest and chemotherapeutic response improvement in gastric cancer." (PMID 39756316, 2024). "S100A11 has the potential as a significant prognostic biomarker for chemotherapy-resistant patients as a higher expression in peripheral blood from tumour-bearing mice after chemotherapy." (PMID 39756316, 2024). "Specifically, the S100A11 gene acts as a tumor promoter by regulating MMP activity and the epithelial-mesenchymal transition (EMT) process." (PMID 38328306, 2023). "S100A11 was expressed only in tumor tissues from the TCGA database, with the highest in CESC and the lowest in LGG." (PMID 36605485, 2023). "S100A11 is a member of the S100 protein family and has high homology with calmodulin and EF-hand calcium-binding proteins, which promotes tumor progression through cell proliferation, metastasis, angiogenesis and immune evasion." (PMID 36605485, 2023). "Our work confirmed the expression of S100A11 not only in tumor cells, but also in macrophages, Tregs, Endothelial cells and fibroblasts, indicating a potential function of S100A11 in these immune cells." (PMID 36605485, 2023). "S100A11 has been found to be involved in regulating inflammation, cell proliferation, differentiation, and tumor development through binding to Toll-like receptor 4 (TLR4)." (PMID 37510130, 2023). "At present, research of S100A11 is mainly focused on tumor cells, its relationship with immunosuppressive cell, such as TAMs, TAFs, and Tregs, was still unclear." (PMID 36605485, 2023). "The loss of PCK1 results in the enhancement of S100A11, which recruits AKT1 to facilitate the activation of the PI3K/AKT signaling pathway, thereby promoting tumor progression." (PMID 37166978, 2023). "The expression of S100A11 was significantly related to immunosuppressive genes and immune checkpoints in most tumor types." (PMID 36605485, 2023). "Previous studies demonstrated that S100A11 played a crucial role in tumor and low-grade inflammation." (PMID 37059863, 2023). "A statistically significant correlation was found between S100A11 and S100P (R = 0.73), both in cell lines and in the tumor array (R = 0.62)." (PMID 37627239, 2023). "The upregulation of S100A11 has been found to accelerate tumor cell proliferation, migration, and invasion by activating several signaling pathways." (PMID 35510040, 2022). "Similar results were obtained by TCGA analysis, with the expression level of S100A11 in tumour tissues being significantly higher than in paracancerous tissues and there being poor prognosis in the cohort with high S100A11 expression." (PMID 35752610, 2022). "Then, the frequency of CSC was calculated, which indicated that S100A11 downregulation significantly reduced its frequency to 1 in every 214,408 cells in BxPC3, whereas 1 in 49,326 control cells had the ability to form tumours." (PMID 35752610, 2022).
tumor (continued). "We demonstrate that S100A11 plays its role as a tumour promoter through regulating the MMP activity and the epithelial-mesenchymal transition (EMT) process." (PMID 33931048, 2021). "It was identified as a tumor-derived EVP protein involved in eliciting immune responses, suggesting that S100A11 is also involved in tumor immunity." (PMID 34179021, 2021). "These seemingly contradictory results support the notion that elevated S100A11 is beneficial only for early diagnosis of PC; however, S100A11 can also be used as a tumor suppressor gene in PC development." (PMID 34527585, 2021). "Taken together, the immunohistochemistry data demonstrate that S100A11 protein is expressed at higher levels in tumour tissue with stage and grade dependence." (PMID 33931048, 2021). "An increasing number of papers have reported that S100A11 behaves as a tumour promoter in prostate, pancreatic, breast, ovarian and colorectal carcinoma, but inhibits tumour progression in bladder cancer." (PMID 33931048, 2021). "The present study sheds light on the role of S100A11 in tumor progression and chemoresistance in GC." (PMID 33931048, 2021). "More importantly, the S100A11-specific targeting potentially presents dual therapeutic benefits by not only controlling tumour progression but also sensitising chemotherapeutic cytotoxic response." (PMID 33931048, 2021). "In our study, the results showed that the expression of S100A11 was significantly upregulated in HCC tissues than in para-tumor tissues." (PMID 33815482, 2021). "Although S100A11 is upregulated in CRC tumor tissue, the serum level of S100A11 is lower in CRC patients." (PMID 34563043, 2021). "Previous studies suggest that S100A11 plays a role in a variety of physiological processes in tumours which include regulation of cell differentiation, invasion, migration cell cycle and apoptosis." (PMID 33931048, 2021). "S100A11 is involved in many types of cancers and it plays a distinct role depending on the specific tumor type." (PMID 34179021, 2021). "The gene expression profile analysis demonstrated that the levels of S100A4/S100A6/S100A10/S100A11/S100A13/S100P were higher in tumor than in normal liver samples." (PMID 33815482, 2021). "In summary, we reveal the role of S100A11 in GC and the relationship between S100A11 and chemotherapy resistance in human tumours." (PMID 33931048, 2021). "The high intensity of the S100A11 staining was observed more in the higher grade tumour tissue as well." (PMID 33931048, 2021). "Similar observations were made for S100A11, as the expression is detected in the earlier stages and seems to decrease during tumour progression." (PMID 32722137, 2020). "S100A11 is located in the cytoplasm of tumor cells and highly expressed in CRC tissues compared with adjacent normal tissues." (PMID 33294444, 2020). "S100A11 has dual functions: it acts as tumour suppressor or tumour promoter on different tumour type." (PMID 31430050, 2019). "It was reported that the A549 and LTEP-a-2 cell lines, which have lost S100A11 expression, show a marked suppression in tumor growth, and S100A11 knockdown also significantly inhibited tumor growth in vivo." (PMID 29607329, 2018). "We also validated concordant protein expression of EIF3C and S100A11 on HCC tumor tissues by IHC assays." (PMID 29568350, 2018). "We subcutaneously injected tumor cells and the anti-S100A11 antibody, and evaluated the effect of the antibody on the tumorigenic potential." (PMID 29362358, 2018). "Compared to control group, more and larger tumor nodules were found in the lung of mice with S100A11-overexpressing groups with cytoplasmic or nuclear localization." (PMID 27181092, 2016). "The role of S100A11 is complex and it can act either as a tumour suppressor or as a tumour promoter in different types of tumours." (PMID 26880885, 2016).
tumor (continued). "It is of considerable importance that gene expression of S100a4 and S100a11 was up to 34-fold induced in tumours of EGF transgenic mice, however expression of S100a1 was repressed." (PMID 25872475, 2015). "We observed the up-regulation of S100A11 protein which functions in tubulin polymerization, motility, and tumor invasion and down-regulation of the transforming acidic coiled-coil-containing protein 3 (TACC3)." (PMID 24628760, 2014). "S100A11 is one of the essential proteins for pseudopod protrusion and tumour cell migration and invasion." (PMID 24376686, 2013). "S100A6 and S100A11 can discriminate significantly between the two primary tumor entities, CRC and HCC, whereas S100A6 allows the discrimination of metastases and HCC." (PMID 19048101, 2008). "Notably, combined knockout of S100A11 in both tumor cells and CAFs produced a more pronounced therapeutic effect than knockout in tumor cells alone." (PMID 41154598, 2025). "Moreover, we examined the S100A11 expression in published CRC single-cell sequencing data and confirmed that S100A11 is highly expressed in CRC tumor cells." (PMID 40515555, 2025). "For instance, CXCL14 may suppress tumor growth, while S100A11 promotes cancer cell survival and migration." (PMID 41182757, 2025). "Tumor growth generated by S100A11-knockout cells was significantly attenuated compared to controls." (PMID 40567612, 2025). "S100A11, a member of the S100 protein family with calcium ion-binding capabilities, is involved in various cellular processes, including proliferation, differentiation, apoptosis, and tumor formation." (PMID 40427733, 2025). "To verify whether S100A11 is expressed in CRC tumor cells, we explored the CNV profile of the spots with S100A11L40P mutation and found them to have significant genome alterations." (PMID 40515555, 2025). "The inhibition of senescence by S100A11 could therefore represent a critical step in cancer progression, facilitating unchecked cell division and tumour growth." (PMID 40374593, 2025). "Notably, single-cell RNA sequencing (RNA-seq) analysis showed that S100A11 was highly expressed in CRC tumor cells, indicating a potential therapeutic target of S100A11L40P." (PMID 40515555, 2025). "Conversely, S100A11 downregulation appears to restrain tumor growth." (PMID 40841353, 2025). "The differential expression patterns observed in normal versus tumour tissues further support the role of USP14 in modulating S100A11 protein stability, which may impact cellular processes such as proliferation and metastasis." (PMID 40374593, 2025). "This suggests that S100A11 may regulate the tumor immune microenvironment by affecting the infiltration and activity of these immune cells." (PMID 40567612, 2025). "In vivo tumorigenicity assay by subcutaneous inoculation of shS100A11 and non-target control (NTC) HCC cells respectively in NOD-SCID mice showed that S100A11 knockdown in both HCC cell lines significantly reduced the tumor incidence, indicating the role of S100A11 in tumor initiation and growth." (PMID 38169544, 2024). "There was a mild trend for reduction in tumor mass upon S100A11 knockdown." (PMID 38169544, 2024). "S100A11 overexpression may be involved in part of the cancer’s aggressive shifting in such a stressed tumor context." (PMID 38842658, 2024). "In addition, correlations were also noted in the tumor array between S100A11 and S100A2 (R = 0.54), S100A4 (R = 0.46), S100A6 (R = 0.49), S100A13 (R = 0.67), S100A14 (R = 0.65), and S100A16 (R = 0.78)." (PMID 37627239, 2023). "They further found that S100A11 could accelerate tumor progression by regulating MMP activity as well as the EMT process." (PMID 38129538, 2023). "Moreover, S100A11 expression in pan-cancer was significantly related to most immunosuppressive cells, such as tumor-associated macrophages (TAM), tumor-associated fibroblasts (TAF), and Treg cells." (PMID 36605485, 2023). "The increased expression of S100A11 was closely related to tumor immunosuppressive TME." (PMID 36605485, 2023).